CLCNKB (chloride voltage-gated channel Kb)
Description:
Anion-selective channel permeable to small monovalent anions with ion selectivity for chloride > bromide > nitrate > iodide. Forms a homodimeric channel where each subunit has its own ion conduction pathway. May conduct double-barreled currents controlled by two types of gates, two fast gates that control each subunit independently and a slow common gate that opens and shuts off both subunits simultaneously. Assembles with the regulatory subunit BSND/Barttin for sorting at the basolateral plasma membrane domain and functional switch to the ion conducting state. CLCNKB:BSND channels display mostly a linear current-voltage relationship controlled by common gate. Mediates chloride conductance along nephron segments, namely the thick ascending limb of Henle's loop, convoluted tubule and the collecting duct, contributing to the maintenance of systemic acid-base and electrolyte homeostasis (By similarity). Conducts chloride currents in the stria vascularis of the inner ear to establish the endocochlear potential necessary for normal hearing.
Synonyms: hClC-Kb; CLCKB; ClC-K2; ClC-Kb
Tractability: Small molecule: it belongs to a druggable protein family. Antibody: UniProt places it where antibodies can reach, with high confidence; its Gene Ontology location is reachable by antibodies, with high confidence; UniProt predicts a signal peptide or a membrane-spanning region.
Gene: Protein-coding gene on chromosome 1 (16,040,252 to 16,057,367, forward strand). Ensembl gene ENSG00000184908.
Subcellular location: Basolateral cell membrane
Pathways (Reactome):
Transport of small molecules: Stimuli-sensing channels
Gene Ontology:
Molecular function: chloride channel activity; protein binding; voltage-gated chloride channel activity; chloride transmembrane transporter activity
Biological process: renal sodium ion absorption; chloride transport; renal absorption; transepithelial chloride transport; chloride transmembrane transport; transmembrane transport
Cellular component: basolateral plasma membrane; plasma membrane; membrane
Genetic constraint (gnomAD): Loss-of-function variants: 74 observed, 83.78 expected, observed/expected ratio (o/e) 0.88, 90% interval 0.73 to 1.07. The upper end of that interval is the gene's LOEUF score, 1.07, which puts it in group 4 of 6, group 1 being the genes least tolerant of losing a copy. Missense variants: 798 observed, 904.21 expected, observed/expected ratio (o/e) 0.88, 90% interval 0.83 to 0.94. Synonymous variants: 358 observed, 361.07 expected, observed/expected ratio (o/e) 0.99, 90% interval 0.91 to 1.08.
Homologues: Orthologues: chimpanzee CLCNKB (98% identical), macaque CLCNKB (94% identical), dog CLCNK (86% identical), rabbit CLCNKA (85% identical), mouse Clcnka (81% identical), rat Clcnka (81% identical), rat Clcnkb (81% identical), mouse Clcnkb (80% identical), Drosophila melanogaster ClC-a (40% identical), Caenorhabditis elegans clh-3 (37% identical), Drosophila melanogaster ClC-c (24% identical), Caenorhabditis elegans clh-5 (24% identical), and 1 more. Paralogues in human: CLCNKA (91% identical), CLCN2 (45% identical), CLCN1 (41% identical), CLCN4 (25% identical), CLCN5 (24% identical), CLCN3 (24% identical), CLCN7 (23% identical), CLCN6 (22% identical).
Diseases named in the same sentence as CLCNKB in open-access papers:
CLCNKB is named in the same sentence as 43 diseases in open-access papers, as found by Europe PMC text mining. Sharing a sentence is not in itself a finding about the gene and the disease. The quoted sentences say what the papers report.
Bartter syndrome (46 papers, 2008 to 2025). "BS type III, also known as classic Bartter syndrome, is caused by mutations in the CLCNKB gene, which codes for the basolateral chloride channel ClC-Kb." (PMID 39273282, 2024). "Mutations in the CLCNKB gene (1p36), encoding the basolateral chloride channel ClC-Kb, cause type 3 Bartter syndrome." (PMID 39405114, 2024). "Bartter syndrome (BS) type 3 or classic BS is a salt-losing hereditary tubulopathy caused by molecular defects in the CLCNKB gene (MIM * 602023), coding for the basolateral chloride channel ClC-Kb." (PMID 37537162, 2023). "We report a case of Bartter syndrome complicated by chronic kidney disease caused by a new mutation of CLCNKB." (PMID 37063660, 2023). "We report a 14-year-old boy with Bartter syndrome caused by a c.1792C > T (p.Q598*) mutation in the CLCNKB gene." (PMID 37063660, 2023). "Type III Bartter syndrome (BS) is caused by loss-of-function mutations in the gene encoding basolateral chloride channel ClC-Kb (CLCNKB), and is characterized by hypokalemic metabolic alkalosis and hyperreninemic hyperaldosteronism." (PMID 32153641, 2020). "In this study, we identified four patients with clinical manifestations of Bartter syndrome, which expands the spectrum of mutations of the CLCNKB gene in the Chinese population." (PMID 32153641, 2020). "Here we report another aspect of this functional coupling, namely that pendrin KO is functionally coupled with decreases in CLCNKB and Barttin protein abundance, the channel complex mutated in Bartter syndrome." (PMID 35330743, 2020). "CLCNKA has been associated with Bartter syndrome type 4b [MIM #613090] through digenic inheritance in combination with CLCNKB variants." (PMID 32376988, 2020). "Our findings demonstrate deletion of CLCNKB is the most common cause of Bartter syndrome in Iranian patients and we show that age of onset of clinical symptoms as well as clinical features amongst those patients are variable." (PMID 30760291, 2019). "Screening by Whole Exome Sequencing (WES) and long range PCR revealed that 12/17 patients (70%) had a deletion of the entire CLCNKB gene that was previously identified as the most common cause of Bartter Syndrome in other populations." (PMID 30760291, 2019). "This variant of Bartter syndrome is caused by mutations in the chloride voltage‐gated channel Kb (CLCNKB), which results in dysfunction along both the DCT and TAL." (PMID 31496133, 2019). "This was the case in a study by Zelikovic, where a large Bedouin family sharing CLCNKB variant presented clinical characteristics specific for Gitelman syndrome, on the one side of the spectrum, to classic Bartter syndrome, on the other." (PMID 24711981, 2014). "Classical Bartter syndrome (type III) is caused by variants in CLCNKB encoding the kidney-specific basolateral chloride channel for cBS." (PMID 24711981, 2014). "Our findings demonstrate intrafamilial phenotypic heterogeneity, namely the presence of Gitelman syndrome and classic Bartter syndrome phenotypes in kindred’s with CLCNKB c.490G > T mutation." (PMID 24711981, 2014). "Classic Bartter syndrome is a salt-wasting tubulopathy caused by mutations in the CLCNKB (chloride channel Kb) gene." (PMID 24377430, 2013). "The p.Ala204Thr mutation (exon 7) of the CLCNKB gene is a "founder" mutation that causes most of type III Bartter syndrome cases in Spain." (PMID 24058621, 2013). "In the present work, we describe a new case with CLCNKB gene mutations and review the reported cases of classic Bartter syndrome associated with growth hormone deficiency." (PMID 24377430, 2013). "The diagnosis of Bartter syndrome was confirmed by CLCNKB gene analysis, which revealed compound heterozygous mutations with deletion of exons 1 to 3 (derived from his mother) and ΔL130 (derived from his father)." (PMID 24377430, 2013). "The development of renal cysts have been reported in patients with Bartter syndrome, of whom one had a mutation in the CLCNKB gene." (PMID 21941653, 2011).
Bartter syndrome (continued). "More than 50 mutations in the CLCNKB gene have been reported in patients with Bartter syndrome." (PMID 39405114, 2024). "Perhaps even more interesting is the clinical observation that patients with mutations in CLCNKB (Bartter syndrome type 3) often initially present with classical Bartter syndrome, but later in childhood may revert to a Gitelman-like phenotype." (PMID 31517149, 2019). "Several CLCNKB missense mutations have been found in patients with Bartter syndrome." (PMID 25339907, 2014). "Mutations in the CLCNKB gene give the most variable clinical phenotypes from early polyhydramnios and severe neonatal polyuria to classic Bartter syndrome with a delayed diagnosis in childhood and failure to thrive and to the phenotype of Gitelman syndrome without polyuria." (PMID 21941653, 2011). "Mutations in the CLCNKB gene were previously found to be the cause of classic Bartter syndrome." (PMID 18667063, 2008). "Moreover, mutations in the SLC12A3 intron or other genes, like the CLCNKB gene linked with Bartter syndrome, might be alternative molecular defects." (PMID 38333726, 2023). "Bartter syndrome, encompassing types 1–3, stems from mutations in genes such as NKCC2 (SLC12A1), ROMK (KCNJ1), or CIC-Kb (CLCNKB), culminating in hypokalemic alkalosis and hypercalciuria." (PMID 40126616, 2025). "Whole-exome sequencing (WES) excluded pathogenic variants in renal tubulopathy genes including SLC12A3 (Gitelman syndrome), SLC12A1, CLCNKB, BSND, KCNJ1, MAGED2 (Bartter syndrome), and CASR, CLCNKA, KCNJ10 (hypokalemia-associated genes)." (PMID 40893942, 2025). "Bartter syndrome is classified into five major genotypes caused by mutations in different genes, namely SLC12A1, KCNJ1, CLCNKB, CLCNKA, BSND, and MAGED2." (PMID 38238844, 2024). "Five different types of Bartter syndrome have been identified due to inactivating mutations in SLC12A1, KCNJ1, CLCNKB, BSND, or CASR." (PMID 39405114, 2024). "Type 3, classic Bartter syndrome, involves a mutation in CLCNKB, the gene associated with chloride channel-Kb (ClC-Kb)." (PMID 37887299, 2023). "Gitelman syndrome (GS) and Bartter syndrome (BS) type III are both rare, recessively inherited salt-losing tubulopathies caused by SLC12A3 and CLCNKB mutations, respectively." (PMID 33807568, 2021). "Bartter syndrome is caused by mutations in SLC12A1 encoding NKCC2 (type I), KCNJ1 encoding ROMK (type II), CLCNKB encoding ClC‐Kb (type III) or BSDN encoding Barttin (type IV) (OMIM: 601678, 241200, 607364 and 602522, respectively)." (PMID 32603001, 2021). "In recent years, Bartter syndrome has been classified into five types (types I–V) based on the different underlying disease-causing genes SLC12A1, KCNJ1, CLCNKB, BSND and MAGED2." (PMID 32153641, 2020). "Type III and IV Bartter syndromes (BS) are rare kidney tubulopathies caused by loss-of-function mutations in the CLCNKB and BSND genes coding respectively for the ClC-Kb chloride channels and accessory subunit barttin." (PMID 32256370, 2020). "Using STRING tools, the protein-protein interaction analysis showed that SLC12A3 and CLCNKB interact or coexpress in the human Bartter syndrome protein interaction network." (PMID 30999883, 2019). "A complete deletion of CLCNKB gene with additional alterations of the ClCK-A gene leads to a severe form of Bartter syndrome similar to Bartter syndrome type IV." (PMID 21941653, 2011). "However, no additional shared single nucleotide or copy number variants in CLCNKB were identified, and there is no clinical history of salt wasting, a major clinical feature of Bartter syndrome (MIM #613090), in the affected siblings." (PMID 32376988, 2020). "GS is referred to as a mild variant of classic Bartter syndrome (or renal tubular normotensive hypokalemic alkalosis with hypercalciuria; MIM #607364), which is caused by defects in genes encoding chloride channel components, including CLCNKB, chloride voltage-gated channel Ka (CLCNKA), or both." (PMID 30999883, 2019).
Bartter syndrome (continued). "We also tested SLC12A1, KCNJ1, CLCNKB, BSND, CLCNKA/CLCNKB related to Bartter syndrome, showing negative results." (PMID 30558554, 2018).
Bartter syndrome type 3 (18 papers, 2017 to 2025). "For instance, mutations in the CLCNKB gene, which causes Type 3 Bartter syndrome, or in KCNJ10, responsible for EAST (or SeSAME) syndrome, can result in nearly identical lab findings." (PMID 40777730, 2025). "Bartter syndrome type 3 (BS 3) is a monogenic tubulopathy caused by deleterious variants in the chloride channel gene CLCNKB, a high proportion of these being large gene deletions." (PMID 37612755, 2023). "A further GS-like phenotype, including hypomagnesemia and hypocalciuria, has been also associated with mutations in the CLCNKB gene encoding the chloride channel ClC-Kb, the cause of Bartter’s syndrome type III." (PMID 34578838, 2021). "Loss of function of CLCNKB causes Bartter syndrome type 3 (BS3), which clearly establishes CLCNKB as the key exit pathway for chloride in the TAL." (PMID 31664557, 2020). "Homozygous or compound heterozygous mutations in CLCNKB, which encodes the chloride ion (Cl−) channel ClC-Kb, cause Bartter syndrome type III." (PMID 27234911, 2017). "Type III Bartter syndrome (BS) is an autosomal recessive renal tubule disorder caused by loss-of-function mutations in the CLCNKB gene, which encodes the chloride channel protein ClC-Kb." (PMID 28288174, 2017). "CLCNKB deletions are the leading cause of Bartter syndrome type 3 worldwide." (PMID 37612755, 2023). "Bartter Syndrome of Type III is an autosomal recessive disorder caused by mutations in the “CLCNKB,” which encodes the chloride channel protein “CLC‐Kb,” predominantly expressed in the kidneys." (PMID 40756081, 2025). "Bartter syndrome type 3 is caused by mutations in CLCNKB gene, which is found on chromosome 1p36.13 with 20 exons and encodes the ClC-Kb chloride channel protein." (PMID 36092934, 2022). "Bartter syndrome type III results from biallelic mutations in the CLCNKB gene, which encodes the ClC-Kb chloride channel." (PMID 35137195, 2022). "Loss of function mutations in CLCNKB (which encodes ClC-Kb) and BSND (encoding Barttin) are the cause of Bartter syndrome type III and type IV, respectively (see SLC12 section)." (PMID 33192599, 2020). "In this patient two likely pathogenic variants in compound heterozygous state (p.[(?)];[(Glu490Lys)]) in the CLCNKB gene (Chloride Channel Protein ClC-Kb, pathogenic mutations cause type III BS, OMIM #607364) were identified confirming a clinical diagnosed of Bartter syndrome type 3." (PMID 32997713, 2020).
Gitelman syndrome (11 papers, 2014 to 2025). Gitelman syndrome (GS), also referred to as familial hypokalemia-hypomagnesemia, is characterized by hypokalemic metabolic alkalosis in combination with significant hypomagnesemia and low urinary calcium excretion. "Gitelman syndrome (GS) is a rare autosomal recessive salt-losing renal tubular disorder associated with a mutation of SLC12A3 or CLCNKB genes which encodes the thiazide-sensitive sodium-chloride co-transporter (NCCT) in the distal renal tubule." (PMID 37791211, 2023). "In a small minority of Gitelman syndrome patients, mutations in the CLCNKB gene encoding the chloride channel ClC-Kb have been identified." (PMID 32758178, 2020). "Gitelman syndrome is typically caused by mutations in the SLC12A3 gene encoding the thiazide-sensitive NaCl cotransporter or the CLCNKB gene encoding the chloride channel ClC-Kb." (PMID 33625696, 2021).
Hypocalciuria (7 papers, 2017 to 2025). An abnormally decreased calcium concentration in the urine. "Nozu also reported hypocalciuria in all patients with mutations in the CLCNKB gene." (PMID 28288174, 2017). "It has been hypothesized that different mutations in the CLCNKB gene could determine the presence or absence of hypocalciuria or hypercalciuria." (PMID 28288174, 2017).
Hypomagnesemia (7 papers, 2017 to 2025). An abnormally decreased magnesium concentration in the blood. "For the present pedigree, while both I-2 and II-4 carry the same dual homozygous mutations in SLC12A3 and CLCNKB, II-2 had hypomagnesemia, gout and CPPD, whereas II-4 had normal magnesemia and kidney stones." (PMID 33807568, 2021). "However, hypomagnesemia is frequent in patients with pathogenic variants in the CLCNKB gene." (PMID 32997713, 2020). "We describe an inbred family with coexisting hypomagnesemia and hyperuricemia caused by simultaneous homozygous mutations in SLC12A3 and CLCNKB gene." (PMID 33807568, 2021). "The CLCNKB gene is thus listed under the hypercalciuric as well as under the Gitelman-like hypomagnesemias." (PMID 27234911, 2017).
Bartter syndrome type 4 (6 papers, 2015 to 2024). A form of Bartter syndrome characterized by maternal polyhydramnios, premature delivery, salt loss, polyuria and sensorineural deafness, associated with hypokalemic and hypochloremic metabolic alkalosis, increased levels of plasma renin and aldosterone, and low to normal blood pressure. "Bartter syndrome type 4 is a disease in which both CLCNKA and CLCNKB are affected and was found to be associated with biallelic pathogenic mutations of the BSDN gene, coding for the essential Barttin subunit of both the CLCNKA and CLCNKB chloride channels." (PMID 38731822, 2024).
Hypokalemia (5 papers, 2020 to 2025). An abnormally decreased potassium concentration in the blood. "The first younger brother of the proband harbored the same homozygous mutations in CLCNKB and exhibited clinical features of hypokalemia, normomagnesemia, hypercalciuria and hyperuricemia." (PMID 33807568, 2021). "I-1 also carried both heterozygous mutation in SLC12A3 and CLCNKB, which may explain his hypokalemia." (PMID 33807568, 2021). "The two patients were diagnosed early in their infancy with severe hyponatremia, hypokalemia, and hypochloremia, supporting the hypothesis that truncating variants of CLCNKB may be correlated with a severe phenotype in type III BS patients." (PMID 32153641, 2020).
Hypertension (4 papers, 2015 to 2023). The presence of chronic increased pressure in the systemic arterial system. "Previous research has indicated a potential link between CLCNKB polymorphisms and conditions such as hypertension and reduced hearing thresholds." (PMID 38069401, 2023). "Lastly, 12 individuals (four affected) were found to have an exonic heterozygous duplication of the chloride channel, voltage-sensitive Kb (CLCNKB), variants in which are associated with essential hypertension." (PMID 25887117, 2015). "From the DO analysis, the following potential gene targets have been selected, these include CLCNKB, CYPB11B2, SH2B2, STK9, and TBX5 as they show interactions exclusively with hypertension-related pathways." (PMID 33917487, 2021).
nephrocalcinosis (3 papers, 2023 to 2025). Nephrocalcinosis is a disorder that occurs when too much calcium is deposited in the kidneys. "Nephrocalcinosis was noted in all patients with genetically confirmed BS of non-CLCNKB genes and 21% of BS3." (PMID 36993809, 2023).
deafness (2 papers, 2017 to 2020). An inherited or acquired condition characterized by the complete loss of the ability to hear from one or both ears. "Interestingly, only homozygous inactivating mutations in each of the two chloride channels, CLCNKA and CLCNKB, have been associated with deafness, perfectly overlapping with the definition of true digenic effects." (PMID 32150856, 2020). "One interesting and challenging aspect is the number of digenic inheritance reports following the initial case of Bartter syndrome and deafness caused by inactivating biallelic mutations in both CLCNKA and CLCNKB." (PMID 32150856, 2020).